FST (follistatin)
Diseases named in the same sentence as FST in open-access papers (continued):
Sharing a sentence is not in itself a finding about the gene and the disease.
atherosclerosis (2 papers, 2018 to 2019). A disease characterized by the build-up of fatty material and calcium deposition in the arterial wall resulting in partial or complete occlusion of the arterial lumen. "Thus, the competing risk of potential unmeasured risk factors may diminish the relative significance of inflammation, represented by activin A and follistatin, in promoting the atherosclerosis." (PMID 29967428, 2018). "However, clinical data on activin A and follistatin levels in patients with prediabetes, and their associations with atherosclerosis, are lacking." (PMID 29967428, 2018). "We also show for the first time that the serum activin A level, as well as the serum follistatin level, was correlated positively with cIMT in subjects with prediabetes and those with normal glucose levels, which suggests a potential role of activin A in atherosclerosis in prediabetic stages." (PMID 29967428, 2018).
benign breast disease (2 papers, 2009 to 2016). "The present findings suggest a role for follistatin in breast benign disease, particularly in FIB, where its expression was increased in stromal cells." (PMID 19740438, 2009). "The current findings suggest a role for FST in breast benign disease, particularly in FIB, since its expression was increased in the stromal cells of this benign disease." (PMID 19740438, 2009).
breast fibroadenoma (2 papers, 2009 to 2017). "This dissociation has been documented in breast fibroadenoma that overexpressed follistatin but not FSTL3." (PMID 28178680, 2017).
Cachexia (2 papers, 2020 to 2025). Severe weight loss, wasting of muscle, loss of appetite, and general debility related to a chronic disease. "Simultaneously, follistatin therapy can promote muscle hypertrophy and mitigate atrophy in cachexia models." (PMID 40869331, 2025). "Conversely, follistatin, a muscle-derived exerkine that binds and neutralizes myostatin and activin A, is significantly reduced in cachexia." (PMID 40869331, 2025).
Duchenne muscular dystrophy (2 papers, 2017 to 2022). Duchenne muscular dystrophy (DMD) is a neuromuscular disease characterized by rapidly progressive muscle weakness and wasting due to degeneration of skeletal, smooth and cardiac muscle. "Several strategies based on the myostatin-follistatin pathway are currently in clinical trials for muscle pathologies such as Duchenne muscular dystrophy (DMD), Becker muscular dystrophy and inclusion body myositis but have yet to be initiated for SMA." (PMID 28768735, 2017).
glioblastoma (2 papers, 2009 to 2020). The most malignant astrocytic tumor (WHO grade IV). "To validate the expression of follistatin in human gliomas we stained four human glioblastoma multiforme (GBM) grade IV tumors with an antibody recognizing follistatin." (PMID 19558675, 2009). "Significant differences between glioblastoma samples and healthy controls were observed for angiopoietin, follistatin, HGF, IL-8, PDGF-BB, PECAM-1 and leptin, with specificity ranging from 59–81% and sensitivity from 40–88%, while infrared-spectroscopy reached 100% sensitivity and 87.5% specificity." (PMID 33316976, 2020).
glioma (2 papers, 2009 to 2019). A benign or malignant brain and spinal cord tumor that arises from glial cells (astrocytes, oligodendrocytes, ependymal cells). "This cell line was shown to be weakly positive for follistatin in culture in contrast to the gliomas which respond with growth arrest to the NPC." (PMID 19558675, 2009). "Our data implies that the TGFβ family member follistatin is of importance for regulating glioma growth." (PMID 19558675, 2009). "It would be of interest to investigate if the expression of follistatin increases with glioma grade in accordance with follistatin like protein." (PMID 19558675, 2009). "It will be of great importance to test the feasibility of the approach in vivo, to use tools for blocking the actions of follistatin in animals with gliomas and in animals receiving NPC treatments (using e.g. siRNA or antibodies)." (PMID 19558675, 2009). "We evaluated the expression of follistatin in several grade IV human gliomas and found a subpopulation within these tumors which express follistatin." (PMID 19558675, 2009). "This, together with the finding that the addition of recombinant follistatin on tumor cells inhibited N29 proliferation by 30%, might suggest a potential role for follistatin in regulating glioma growth." (PMID 19558675, 2009). "We show that rat gliomas express activin, however there are other TGFβ-family members that might be relevant to look at as potential targets for follistatin regulation, such as the BMPs, which have similar growth and survival regulatory functions." (PMID 19558675, 2009). "This suggests that follistatin has a role in glioma growth and might be of interest as a potential marker for glioma grade as well as for tumor progression." (PMID 19558675, 2009). "The increase in growth after the addition of follistatin antibodies in vitro, or the direct inhibitory effects of recombinant follistatin on glioma proliferation might hence influence important cell maintenance signals or directly impact cell proliferation e.g. by modulating the matrix." (PMID 19558675, 2009). "Specific candidates like follistatin and the Gas6/AXL system, point towards future experiments evaluating them in more detail as targets for future therapy of gliomas." (PMID 19558675, 2009). "Our studies detected five proteins that interacted with Fstl1 in glioma using Co-IP and pulldown experiments, i.e., DIP2A, CD14, BMP4, ActR-IIB, and follistatin, and the mRNA levels of MGMT were only increased in GBM cells transfected with DIP2A-specific siRNA (siDIP2A)." (PMID 30542120, 2019).
Hypertension (2 papers, 2012 to 2022). The presence of chronic increased pressure in the systemic arterial system. "For this study we tested the response of a calorie-restricted Dietary Approaches to Stop Hypertension (DASH) diet on changes in myostatin, follistatin, and mystatin:follistatin ratio levels after 12 weeks in comparison to basline in adults aged 65 years and older." (PMID 35287731, 2022). "Activin A, but not activin B or follistatin, was also significantly elevated in subjects with a history of hypertension (P < 0.001)." (PMID 23304117, 2012).
inflammatory bowel disease (2 papers, 2019 to 2021). A spectrum of small and large bowel inflammatory diseases of unknown etiology. "There is evidence that activin A promotes allergic diseases and inflammatory bowel disease, whereas these effects could be blocked by follistatin." (PMID 31182152, 2019).
injury (2 papers, 2021 to 2022). Damage inflicted on the body as the direct or indirect result of an external force, with or without disruption of structural continuity. "We complement our previous work showing that activin receptor signaling is required for myelination in development, by now demonstrating that increased follistatin levels following perinatal brain injury impair myelination." (PMID 33417729, 2021).
leiomyoma (2 papers, 2023). A well-circumscribed benign smooth muscle neoplasm characterized by the presence of spindle cells with cigar-shaped nuclei, interlacing fascicles, and a whorled pattern. "Leptin induces a tumor-friendly microenvironment through upregulation of pro-inflammatory (IFNγ, IL-8, IL-6, GM-CSF, MCP-1, and TNF-α), fibrotic (TGF-β1, TGF-β2, and TGF-β3), and angiogenic (VEGF-A, HGF, and Follistatin) factors in human leiomyoma cells." (PMID 36771423, 2023). "Another study on leiomyomas showed increased myostatin levels in cancer, but follistatin expression was unaffected compared to healthy controls." (PMID 36901894, 2023).
leukemia (2 papers, 2020 to 2023). A malignant (clonal) hematologic disorder, involving hematopoietic stem cells and characterized by the presence of primitive or atypical myeloid or lymphoid cells in the bone marrow and the blood. "Importantly, serum FST levels were positively correlated with the percentage of leukemia blast in PB from FLT3/ITD‐mutated primary AML patients at diagnosis." (PMID 32134197, 2020). "Perturbation of FST expression significantly reduced leukemia clonogenicity and engraftment in vivo." (PMID 32134197, 2020). "Importantly, antisense oligo targeting FST also reduced leukemia growth in vitro and in vivo, providing an important lead for clinical trials." (PMID 32134197, 2020). "Finally, plasma FST levels might be exploited as a surrogate biomarker of leukemia cell growth to evaluate treatment response to FLT3 inhibitors in FLT3/ITD AML." (PMID 32134197, 2020). "FST targeting by shRNA, CRISPR/Cas9, and antisense oligo suppressed leukemia growth in vitro and in vivo." (PMID 32134197, 2020). "Mechanistically, FST enhanced MAPK/ERK signaling, providing a positive feedback loop that promoted leukemia cell growth in vitro and in vivo." (PMID 32134197, 2020). "Importantly, serum FST positively correlated with leukemia engraftment in FLT3/ITD AML patient‐derived xenograft mice and leukemia blast percentage in primary AML patients." (PMID 32134197, 2020).
metabolic syndrome (2 papers, 2024 to 2025). A cluster of metabolic risk factors for CARDIOVASCULAR DISEASES and TYPE 2 DIABETES MELLITUS. "Spexin, follistatin and measurements of metabolic syndrome parameters were performed at the beginning and after 12 weeks." (PMID 39895162, 2025).
myasthenia gravis (2 papers, 2019 to 2021). Myasthenia gravis (MG) is a rare, clinically heterogeneous, autoimmune disorder of the neuromuscular junction characterized by fatigable weakness of voluntary muscles. "Notably, our analysis also revealed that myoid cells express high levels of follistatin, thus providing insight into why conditions such as myasthenia gravis, which affect myoid cell numbers, perturb human TEC differentiation." (PMID 33597545, 2021).
Myocardial fibrosis (2 papers, 2021 to 2023). "Therefore, maintaining a balance between Act A and follistatin is closely associated with the pathological process of myocardial fibrosis." (PMID 38074154, 2023).
neuroblastoma (2 papers, 2013 to 2016). Neuroblastoma (NB) is the most common solid, extracranial childhood tumor. "The gene LOC101103238 (recently named CXCL5) and follistatin (FST) have been shown to be upregulated in mice inoculated with 22L prions prior to the development of clinical signs and in prion susceptible neuroblastoma cells, correspondingly." (PMID 26807844, 2016). "Follistatin stimulated neurite outgrowth of the neuroblastoma cell line IMR-32." (PMID 23378731, 2013).
osteosarcoma (2 papers, 2017 to 2021). A usually aggressive malignant bone-forming mesenchymal neoplasm, predominantly affecting adolescents and young adults. "In the present study, we explored the use of two different IASPs, a soluble activin type IIA decoy receptor and a follistatin analog, as therapeutics against osteosarcoma in an in vivo intratibial xenograft model." (PMID 33179858, 2021). "In a murine intratibial osteosarcoma xenograft model, two types of inhibitors were tested: (a) a soluble activin type IIA decoy receptor (ActRIIA‐mFc), or (b) a modified variant of follistatin (FSTΔHBS‐hFc), either alone or in combination with a bisphosphonate." (PMID 33179858, 2021). "Moreover, ectopic expression of CDC42BPG, FST344 (major isoform of FST) or FST311 (minor isoform of FST) reduced cell proliferation, which indicated that these genes also had growth suppressive effects in osteosarcoma cell lines." (PMID 28878391, 2017).
ovarian endometriosis (2 papers, 2009 to 2022). A non-neoplastic disorder characterized by the growth of endometrial tissue in the ovaries. "Women with ovarian endometrioma (52 patients) had increased serum follistatin than patients with other benign ovarian cysts (52 patients), patients with non-ovarian endometriosis (11 patients) and healthy controls (27 controls)." (PMID 36289764, 2022). "FLRG was also found to be down-regulated in ovarian endometriosis, while FST expression was found to be up-regulated." (PMID 19740438, 2009). "Notably, women with non-ovarian endometriosis had higher serum follistatin levels than patients with other benign ovarian cysts and healthy controls." (PMID 36289764, 2022).
pituitary adenomas (2 papers, 2021 to 2022). "Differential expression of follistatin, a BMP-binding protein, depending on FSH productivity, was also shown in human pituitary adenomas." (PMID 34681844, 2021).
premature ovarian failure (2 papers, 2022 to 2025). "Animal models have shown that FST deficiency leads to premature ovarian failure, confirming its key role in maintaining pregnancy homeostasis." (PMID 40869979, 2025). "FST isoforms are implicated in uterine development that FST288 isoform is sufficient for the development, and that loss of FST315 isoform results in fertility defects that resemble activin hyperactivity and premature ovarian failure." (PMID 36497076, 2022).
Sepsis (2 papers, 2014 to 2024). Sepsis is defined as life-threatening organ dysfunction caused by a dysregulated host response to infection. "Urinary follistatin may serve as a valuable marker reflecting the severity of acute tubular damage in sepsis-associated AKI and drug-induced AKI." (PMID 38534369, 2024). "Activin A and its binding protein follistatin (FS) are increased in inflammatory disorders and sepsis." (PMID 24885241, 2014).
thymic epithelial tumors (2 papers, 2019 to 2024). "Remarkably, it has been proposed that the root cause of dysregulated serum FST levels might stem from the tumors themselves, as surgical resection of thymic epithelial tumors results in the baseline resetting of FST levels within patient serum." (PMID 38392348, 2024). "In patients with thymic epithelial tumors, there is a noteworthy positive correlation between serum FST levels and the density of mature tumor microvessels." (PMID 38392348, 2024).
Ureteral obstruction (2 papers, 2014 to 2022). Obstruction of the flow of urine through the ureter. "In a previous study, administration of recombinant follistatin, an endogenous activin antagonist, reduced the fibrotic area in rats with unilateral ureteral obstruction kidneys." (PMID 35328214, 2022).
abortion (1 paper, 2023). the ending of pregnancy by removing a fetus or embryo before it can survive outside the uterus. "Establishing a direct causal link between follistatin and spontaneous abortion presents challenges due to confounding effects from factors such as lifestyle and environmental influences." (PMID 38234423, 2023). "Modulating follistatin levels or relevant pathways could hold promise for reducing the incidence of spontaneous abortion and improving reproductive outcomes." (PMID 38234423, 2023). "However, it should be noted that some studies reported no significant decrease of follistatin in the serum of women with spontaneous abortion." (PMID 38234423, 2023).
acute myeloid leukemia (1 paper, 2020). Acute myeloid leukemia (AML) is a group of neoplasms arising from precursor cells committed to the myeloid cell-line differentiation. "Here, embryonic morphogen FST is identified as a novel biomarker and therapeutic target for human FLT3/ITD‐mutated acute myeloid leukemia." (PMID 32134197, 2020).
Allergy (1 paper, 2023). An allergy is an immune response or reaction to substances that are usually not harmful. "The levels of FS (Follistatin), Erb-B2 receptor tyrosine kinase 2 (ERBB2), TGFR2 (transforming growth factor beta receptor 2), MSLN (mesothelin) and TM (thrombomodulin) were influenced by Benzodiazepines and PRS27 (serine protease 27) by allergy drugs." (PMID 37667404, 2023).
anemia (1 paper, 2023). A reduction in the number of red blood cells, the amount of hemoglobin, and/or the volume of packed red blood cells. "FKN induces the secretion of the receptivity-related cytokines at anemia, which may improve endometrium receptivity via the CX3CR1 and the regulation of the NFκB pathway and by regulating activin, follistatin, and BMP2, as well as PR, SOX-17, PTGER2, and TIMP2." (PMID 37175630, 2023).
atrophying (1 paper, 2017). "Here we show that the expression of components of the myostatin signaling pathway is downregulated in muscle wasting or atrophying diseases, with a decrease of myostatin and activin receptor, and an increase of the myostatin antagonist, follistatin." (PMID 29192144, 2017).
benign ovarian tumours (1 paper, 2017). "When comparing OC with benign ovarian tumours, six markers had statistically different expression (osteopontin, leptin, follistatin, PDGF-AB/BB, HGF, FGF-basic)." (PMID 28075407, 2017).
Burkitt lymphoma (1 paper, 2024). A rare form of malignant mature B-cell non-Hodgkin lymphoma. "For instances of drug-induced AKI or AKI associated with Burkitt lymphoma accompanied by tumor lysis syndrome, urinary follistatin levels returned to baseline prior to the normalization of serum creatinine levels." (PMID 38534369, 2024).
cardiomyopathy (1 paper, 2023). A disease of the heart muscle or myocardium proper. "myofibrils-related cardiomyopathy, skeletal muscle fiber contraction, negative regulation of proteolysis, and follistatin-myostatin regulation were identified." (PMID 37468461, 2023).
cholesteatoma (1 paper, 2023). A pathologic process characterized by the proliferation of keratinizing squamous epithelium resulting in the accumulation of keratin and cells in the middle ear and/or mastoid. "Moreover, follistatin, an antagonist of activin A, reduces osteoclastogenesis and resultant bone erosion in cholesteatoma." (PMID 37537159, 2023).
colorectal cancer (1 paper, 2021). A primary or metastatic malignant neoplasm that affects the colon or rectum. "Spearman’s Correlations between the clinicopathological characteristics of fresh colorectal cancer samples (n = 40) and intratumoral concentrations of mature activins and follistatin." (PMID 34867090, 2021). "This study explored the roles of activins and follistatin in colorectal cancers." (PMID 34867090, 2021).
cyst (1 paper, 2015). A sac-like closed membranous structure that may be empty or contain fluid or amorphous material. "Further studies are needed to elucidate why the three isoforms of FST act differently on the two types of cells during mice cyst break down and primordial folliculogenesis." (PMID 26076381, 2015). "The role of FST288, the strongest ACT-neutralizing isoform of follistatin (FST), during cyst breakdown and primordial follicle formation in the fetal mice ovary was assessed using an in vitro culture system." (PMID 26076381, 2015).
diabetic cardiomyopathy (1 paper, 2021). Diabetic cardiomyopathy is a disorder of the heart muscle in people with diabetes. "To examine FST expression in diabetic cardiomyopathy, we assessed the level of FST in the serum of diabetic cardiomyopathy patients, and the FST level in db/db mouse serum and heart tissue was also assessed." (PMID 34385917, 2021). "Our study has demonstrated that FST is an important molecule involved in the development of diabetic cardiomyopathy." (PMID 34385917, 2021). "FST could bind and block the function of activin A; thus, the increased ratio of activin A/FST may suggest increased signaling through activin A–activated mechanisms in diabetic cardiomyopathy." (PMID 34385917, 2021).